TRPM2 (transient receptor potential cation channel subfamily M member 2)
Diseases named in the same sentence as TRPM2 in open-access papers (continued):
Sharing a sentence is not in itself a finding about the gene and the disease.
gastric cancer (23 papers, 2018 to 2025). A primary or metastatic malignant neoplasm involving the stomach. "TRPM2 was found to be expressed on mRNA level in gastric cancer patients, and its high expression was negatively associated with the overall survival of patients." (PMID 32182937, 2020). "In fact, it has been recently proven that TRPM2 causes an increase in MMP-9 production in gastric cancer." (PMID 33132914, 2020). "TRPM2 controls calcium influx in gastric cancer cells, which suppresses the ability of PTEN to negatively regulate the PI3K/AKT signaling pathway, thus fostering the EMT process." (PMID 39633507, 2024). "In gastric cancer cells, silencing of the transient receptor potential melastatin-2 (TRPM2) increases the levels of ROS, iron, and lipid peroxides, resulting in ferroptosis." (PMID 38424190, 2024). "Outcomes proved that TRPM2 is practically expressed like a plasma membrane ion channel which is penetrable to Ca2+ in gastric cancer cells along with its impediment lowered cell bioenergetics, inhibited cell invasion, and declined cell survival." (PMID 37337283, 2023). "By authors, two shRNA (short hairpin RNAs) were administered against TRPM2 to lower the expression and role in gastric cancer, AGS, and MKN45." (PMID 37337283, 2023). "Akt activation is known to lie downstream of TRPM2 activation in different models, including gastric cancer cell and aortic smooth muscle cells." (PMID 38390373, 2023). "Using molecular and functional assays, one study has demonstrated that downregulated TRPM2 significantly prevents the movement and invasion capacities of gastric cancer cells, including a significant decline in the expression of metastatic markers." (PMID 37337283, 2023). "Altogether, the known outcomes offer convincing information on the vital role of TRPM2 to modulate the gastric cancer cell invasion presumably by monitoring the PTEN/Akt pathway." (PMID 37337283, 2023). "The authors recognized that to facilitate gastric cancer survival TRPM2 functions through JNK-dependent as well as mTOR-independent pathways of autophagy." (PMID 37337283, 2023). "TRPM2 expression has a considerable role in gastric cancer cells’ bioenergetics and survival, according to confirmation from current numerous investigations." (PMID 37337283, 2023). "Due to its effects on autophagy, TRPM2 downregulation sensitizes gastric cancer cells to paclitaxel and doxorubicin treatment." (PMID 36158191, 2022). "In gastric cancer, TRPM2 downregulation inhibited migration and invasion and was associated with decreased EMT markers, integrins, Akt phosphorylation and increased PTEN." (PMID 36446940, 2022). "Another study revealed that TRPM2 can promote migration of gastric cancer, invasion, and tumor growth by regulating PTEN/Akt pathway mediated epithelial-mesenchymal transition (EMT)." (PMID 36371178, 2022). "A number of studies revealed that inhibition or genetic deletion of TRPM2 significantly enhances anti-cancer drug cytotoxicity in neuroblastoma, breast and gastric cancers." (PMID 35207698, 2022). "In gastric cancer, the knockdown of TRPM2 inhibited autophagy process, thus sensitizing gastric cancer cells to paclitaxel and doxorubicin." (PMID 35207698, 2022). "The survival of gastric cancer (GS) patients has negatively been correlated to the TRPM2 expression." (PMID 36844925, 2022). "The PTEN/Akt signaling pathway is also required in TRPM2-modulated migration and invasion of gastric cancer cells." (PMID 36446940, 2022). "TRPM7 is essential for the survival of AGS cells 26, 27, and TRPM2 has the ability to control the invasion of gastric cancer cells." (PMID 33859522, 2021). "Functional TRPM2 is expressed in gastric cancer cell lines AGS and MKN-45, and its shRNA based knockdown results in the inhibition of proliferation and enhancement of apoptosis." (PMID 32182937, 2020).
gastric cancer (continued). "For instance, inhibition of TRPM2 expression or function increased the cytotoxic effect of paclitaxel and doxorubicin in breast and gastric cancer cells." (PMID 32575381, 2020). "Transient Receptor Potential Melastatin-2 (TRPM2) ion channel is emerging as a great therapeutic target in many types of cancer, including gastric cancer – a major health threat of cancer related-death worldwide." (PMID 30862883, 2019). "Here, using molecular and functional assays, we demonstrate that TRPM2 downregulation significantly inhibits the migration and invasion abilities of gastric cancer cells, with a significant reversion in the expression level of metastatic markers." (PMID 30862883, 2019). "Taken together, our results provide compelling evidence on the important function of TRPM2 in the modulation of gastric cancer cell invasion likely through controlling the PTEN/Akt pathway." (PMID 30862883, 2019). "TRPM2 was also proved to preserve gastric cancer cell survival via the JNK-signaling pathway." (PMID 37608401, 2023). "Furthermore, TRPM2 enhances the migration, invasion and tumorigenesis of gastric cancer cells by decreasing PTEN activity and increasing Akt signaling." (PMID 36158191, 2022). "In gastric cancer, integrins were also decreased after reduction in endogenous TRPM2." (PMID 36446940, 2022). "Moreover, TRPM2 silencing inhibited tumor formation by gastric cancer cells in a xenograft mouse model." (PMID 34360952, 2021). "Functional expression of TRPM2 was also observed in gastric cancer." (PMID 34360952, 2021). "Similarly, it was previously reported that TRPM2 knockdown significantly enhances gastric cancer cell sensitivity to PAX which validates its therapeutic potential as an anticancer target." (PMID 30984336, 2019). "Our previous study demonstrated the critical role of TRPM2 in gastric cancer cells bioenergetics and survival; however, its role in gastric cancer metastasis, the major cause of patient death, remains unknown." (PMID 30862883, 2019). "In addition, the authors stated that there is a correlation with the lower overall survival rate of patients particularly in late/advanced phases thus demonstrating the probability of possible function of TRPM2 as a prognostic biomarker for the late phase of gastric cancer." (PMID 37337283, 2023). "Thus, we could speculate a TRPM2-Akt-Rac1 axis in the modulation of MMP-9 expression in gastric cancer." (PMID 33132914, 2020). "Moreover, TRPM2 downregulation sensitized gastric cancer cells to paclitaxel and doxorubicin." (PMID 30884858, 2019). "Thus, TRPM2 knockdown inhibits cell proliferation, and promotes apoptosis in gastric cancer cells." (PMID 29875336, 2018). "After down-regulation of TRPM2 with shRNA in AGS and MKN-45, two gastric cancer cell lines, the cells developed slowly, and the proportion of apoptotic cells raised." (PMID 37337283, 2023). "Moreover, silencing of TRPM2 concluded the deregulated metastatic markers and lost the tumor growing capacity of AGS gastric cancer cells within NOD/SCID mice." (PMID 37337283, 2023). "TRPM2 expression within tumors has a negative correlation with the overall survival of patients suffering from gastric cancer." (PMID 37337283, 2023). "However, additional research are required to confirm the significance of TRPM2 and TRPM5 in the survival and clinical outcomes of patients with gastric cancer." (PMID 37337283, 2023). "Indeed, TRPM2, by activating both Akt and JNK signalling pathways, promote gastric cancer cell survival." (PMID 30884858, 2019). "Finally, TRPM2 silencing resulted in deregulation of metastatic markers and abolished the tumor growth ability of AGS gastric cancer cells in NOD/SCID mice." (PMID 30862883, 2019). "Gastric cancer (GC): Erastin and RSL3 upregulate the cation channel transient receptor potential melastatin-2 (TRPM2) in GC cell lines." (PMID 38072908, 2023).
gastric cancer (continued). "Indeed, the lack of the TRPM2 channel down-regulates the JNK-signaling pathway, and impairs autophagy, ultimately causing the accumulation of damaged mitochondria, and the death of gastric cancer cells." (PMID 29875336, 2018).
ischemic stroke (22 papers, 2017 to 2026). A stroke disorder caused by obstruction of blood flow to the brain, due to thrombotic (local blood clot formation) or embolic (due to a blood clot or other material traveling from another site) event. "Gene deficiency of TRPM2 in the peripheral immune system ameliorated neurological outcome and reduced infarct volume in a murine ischemic stroke model." (PMID 38308007, 2024). "​Mechanistically, TRPM2-mediated ischemic stroke has been associated with the expression and signalling of NMDARs." (PMID 37576339, 2023). "Here, we will discuss the distribution, expression, structure, and activation of TRPM2 with a focus on the underlying molecular mechanisms in ischemic stroke pathogenesis." (PMID 33455532, 2021). "Previous studies demonstrated that TRPM2 expression was abundant in the central nervous system (CNS) and was associated with neurodegenerative disease including ischemic stroke." (PMID 33455532, 2021). "Therefore, in the following sections, we summarize recent research progress toward understanding the causes and consequences of pathological TRPM2 activation associated with ischemic stroke." (PMID 33455532, 2021). "Cooperation between immune and neuronal TRPM2 influences the outcome of neuroimmune interaction and many diseases such as infection, inflammation, ischemic stroke, pain, and neurodegenerative diseases." (PMID 41511359, 2026). "Sex-specific response of TRPM2 channels in models of ischemic stroke has been extensively studied, with clear evidence of androgen regulation in male brain and no impact of sex-steroid signaling in the female bran." (PMID 40352737, 2025). "Research has found that TRPM2 in brain endothelial cells exacerbates neuronal death during ischemic stroke by promoting Ca2+ influx and interacting with CD36, thereby disrupting the blood-brain barrier (BBB)." (PMID 39007141, 2024). "The following few studies represented the role of TRPM2 in ischemic stroke models.TRPM2 in primary cortical cultures of rat subjected to H2O2 induces apoptosis, and this is significantly reversed by using TRPM2 siRNA by inhibiting Ca2+ influx and cell death." (PMID 39329114, 2024). "Bilirubin has been found to act as an endogenous agonist of TRPM2, specifically binding to and activating the channel, thereby exacerbating brain damage during ischemic stroke." (PMID 39007141, 2024). "Interventions targeting the uncoupling of TRPM2-NMDAR can effectively mitigate ischemic stroke damage." (PMID 39007141, 2024). "In brain I/R, as typified by ischemic stroke, TRPM2 activation has been found to mediate brain injury through multiple mechanisms." (PMID 39007141, 2024). "TRPM2 is widely expressed in neurons and its role in ischemic stroke was evaluated in several in vitro and in vivo studies." (PMID 39329114, 2024). "TRPM2 contributes to brain injury in ischemic stroke, possibly due to its ability to regulate NMDAR trafficking." (PMID 37631001, 2023). "Given the potential link between the Ca2+/ROS system and TRPM2 on the one hand and NMDAR-mediated ischemic stroke on the other, the role of TRPM2 in ischemic stroke has been investigated in detail." (PMID 37576339, 2023). "In particular, TRPM2-NMDAR coupling is enhanced subsequent to ischemic stroke, resulting in a Protein Kinase C gamma (PKC-γ)-dependent increase in NMDAR expression at the cell surface." (PMID 37631001, 2023). "discover that bilirubin directly gates the opening of TRPM2 channels as an endogenous agonist to aggravate brain damage in ischemic stroke." (PMID 36921602, 2023). "The results of above studies strongly suggest the critical role of TRPM2-mediated Ca2+ signaling in promoting the detrimental microglial/astrocyte activation and microglial/astrocyte-mediated tissue damage after ischemic stroke." (PMID 35159300, 2022). "Here, we give a concise review of the role of TRPM2 in the development and/or progression of these etiological factors of ischemic stroke." (PMID 35159300, 2022).
ischemic stroke (continued). "Recently, we also found that TRPM2-mediated Ca2+ influx is required for TSP1 mediated endothelial dysfunction during ischemic stroke (unpublished)." (PMID 35159300, 2022). "Studies have shown that TRPM2 activation in each component of the NVU can aggregate brain damage during ischemic stroke." (PMID 35159300, 2022). "In recent years, growing evidence has provided insight that TRPM2 played prominent roles in cellular damage and mediated brain injury in ischemic stroke due to their sensitivity to oxidative stress." (PMID 33455532, 2021). "We also present recent progress and challenges in potential treatments targeting TRPM2 in ischemic stroke." (PMID 33455532, 2021). "This review provides data on the expression, structure, and function of TRPM2 and illustrates its cellular and molecular mechanisms in ischemic stroke." (PMID 33455532, 2021). "Following this logic, we propose that TRPM2 can be a potential target for preventing ischemic stroke." (PMID 33455532, 2021). "Similarly, disruption of TRPM2-NMDARs or TRPM2-PKCγ interactions protected the mice against ischemic stroke." (PMID 41511359, 2026). "TAT-M2PBM, a peptide that disrupts TRPM2-protein kinase C γ (PKCγ), a cell-permeable peptide that disrupts TRPM2-PKCγ coupling, significantly inhibits eNMDARs-mediated excitotoxicity and produces potent protection against ischemic stroke in vitro and in vivo." (PMID 40389567, 2025). "TRPM2 was found to increase the expression of GluN2b while decreasing the expression of GluN2a, and knockout of TRPM2 reversed this change and protected mice from ischemic stroke." (PMID 35159300, 2022). "Moreover, the expression of TRPM2 after ischemic stroke was significantly increased, highlighting the critical role of TPRM2 in promoting brain damage." (PMID 35159300, 2022). "Reactive oxygen species (ROS)-induced, TRPM2-dependent, delayed neuronal cell death may represent a common mechanism in ischemic stroke." (PMID 35055089, 2022). "Similarly, specific deletion of TRPM2 in immune cells markedly decreased immune-cell invasion into the brain after ischemic stroke." (PMID 35159300, 2022). "TRPM2 could be a promising target in screening more effective prophylactic strategies and therapeutic medications for ischemic stroke." (PMID 35159300, 2022). "Based on in vitro and in vivo models of ischemic stroke, different neuronal molecular mechanisms might be responsible for the allosteric regulation of TRPM2." (PMID 33455532, 2021). "Ischemic stroke-induced TRPM2 activation leads to extracellular zinc ions significantly increased." (PMID 33455532, 2021). "Taken together, TRPM2 can exacerbate systemic immune response in ischemic stroke." (PMID 33455532, 2021). "In the disease model of ischemic stroke, TRPM2 mRNA levels were significantly elevated." (PMID 33455532, 2021). "These insights about TRPM2 may be the key to find potent therapeutic approaches for the treatment of ischemic stroke." (PMID 33455532, 2021). "Hence, there is an urgent need to develop effective and specific neuroprotective agents targeting TRPM2 for attenuating ischemic stroke." (PMID 33455532, 2021). "Thus, TRPM2 in endothelial cells may represent a safer and more effective therapeutic target for ischemic stroke." (PMID 39007141, 2024). "Thus, the TRPM2-PKCγ uncoupling may also represent an effective therapeutic strategy for reducing NMDAR-mediated excitotoxicity in ischemic stroke." (PMID 39007141, 2024). "However, the failure of targeting NMDA receptors in the treatment of ischemic stroke is shifting researchers’ attention to exploring other molecular mechanisms contributing to neuron death, among which TRPM2 emerges as a pivotal molecule in aggregating neuron death." (PMID 35159300, 2022). "Combination of TRPM2-specific inhibitors with highly tissue/cellular specific nano-delivery vehicles could make possible the application TRPM2-inhibition therapies in treating ischemic stroke and its “upstream” diseases." (PMID 35159300, 2022).
ischemic stroke (continued). "Therefore, TRPM2 is likely to contribute to microglia activation after ischemic stroke." (PMID 35159300, 2022). "Therefore, TRPM2 could be a promising target for screening more effective therapies for preventing ischemic strokes and for treating patients with ischemic stroke." (PMID 35159300, 2022). "Thus, TRPM2 has emerged as a new therapeutic target for ischemic stroke." (PMID 33455532, 2021). "Thus, regulating TRPM2 activation at the molecular level may provide insights into developing new therapeutics for ischemic stroke." (PMID 33455532, 2021). "Therefore, ROS-induced TRPM2-dependent delayed neuronal cell death may represent a common mechanism in ischemic stroke." (PMID 33455532, 2021). "However, the precise molecular mechanisms involved in TRPM2-mediated ischemic stroke remain completely unknown." (PMID 33455532, 2021). "Therefore, we speculate that inhibition of zinc influx and TRPM2 activation by NAC may have a potential for the treatment of ischemic stroke." (PMID 32825703, 2020). "Intriguingly, TRPM2 has been shown to be the primary mediator of ROS-dependent BBB degradation in several brain disorders, including ischemic stroke and Alzheimer’s disease." (PMID 41488927, 2025). "Like TRPM2, NMDAR is also a Ca2+-permeable channel and Ca2+ overload mediated by NMDAR has long been thought to be responsible for neuron death during ischemic stroke." (PMID 35159300, 2022). "TRPM2, TRPV2, and TRPV4 exacerbate neuroinflammation and worsen outcomes in ischemic stroke." (PMID 41399206, 2025). "TRPM2, TRPV2, and TRPV4 exacerbate ischemic stroke, while TRPM8 plays a protective role." (PMID 41399206, 2025). "In addition to TRPM2, TRPM4 and TRPM7 are also highly expressed in the brain, and were found to aggravate the brain injury following ischemic stroke." (PMID 35159300, 2022). "Utilizing the TRPM2-derived interfering peptide TAT-EE3, the authors demonstrated that disruption of the TRPM2-NMDAR interaction effectively prevented phosphorylated CREB and ERK1/2 levels, inhibited neuronal excitotoxicity, and protected mice from ischemic stroke in vitro and in vivo." (PMID 37576339, 2023). "The ‘EE3’ motif of TRPM2 and the ‘KKR’ motif of the NMDAR mediate their interaction, which—when disrupted using an EE3 motif peptide—can protect cultured neurons from oxygen glucose deprivation (OGD)-induced neuronal death in vitro and can reduce brain damage following ischemic stroke." (PMID 37631001, 2023). "Moreover, we also found that endothelial-specific deletion of TRPM2 significantly alleviated plasma extravasation and immune-cell infiltration after middle cerebral artery occlusion (MCAO), in an in vivo mimic of human ischemic stroke in mice (under revision)." (PMID 35159300, 2022). "In this review, we demonstrate that transient receptor potential cation channel, subfamily M, member 2 (TRPM2), a non-selective ion channel activated by oxidative stress, is actively involved in all the important steps in the etiology and pathology of ischemic stroke." (PMID 35159300, 2022).